SLAMF6 (SLAM family member 6)
Diseases named in the same sentence as SLAMF6 in open-access papers (continued):
Sharing a sentence is not in itself a finding about the gene and the disease.
breast carcinoma (4 papers, 2024 to 2025). "Another TCGA analysis that assessed core genes associated with breast cancer status revealed SLAMF6/CD352 as one of eight core genes." (PMID 38476238, 2024). "Single-cell profiling of breast cancer tumor microenvironment reveals SLAMF6 expression overlaps CD8 T cells with a T-effector signature, which includes subsets expressing TCF7, memory and effector-related genes, analogous to progenitor-exhausted T cells." (PMID 38287061, 2024). "In breast cancer, cDC1-related genes were substantially upregulated in the high SLAMF6 group than in the low SLAMF6 group except for THBD." (PMID 38287061, 2024). "scRNA-seq analysis of existing human breast cancer dataset demonstrates that subsets of T cells co-expressing SLAMF6, TCF7, memory- and exhaustion-related genes comparable to progenitor-exhausted T cells identified in pre-clinical models and human melanomas." (PMID 38287061, 2024). "We found that SLAMF6 expression was highly correlated not only with the expression of T-cell markers (CD3E, CD8B, CD8A, and CD4) but also with upregulation of TCF7, PDCD1 encoding PD-1, GZMK, and effector-associated genes including IFNG and PRF1 in breast cancer." (PMID 38287061, 2024). "Consequently, CD8+ T-cell effector (Teff) score, comprising gene expression of IFNG, PRF1, CD8A and CD8B, and BATF3-DC score, calculated with the expression level of BATF3, IRF8, THBD, CLEC9A, and XCR118 were markedly increased in the high SLAMF6 group than in the low SL AMF6 group in breast cancer." (PMID 38287061, 2024).
viral infection (4 papers, 2021 to 2024). "We further found that heterogeneity within the SLAMF6+ subsets might exist, which include a population expressing high levels of MKI67 resembling Slamf6+Ki67+ cells displaying vigorous expansion in response to viral infection in pre-clinical models." (PMID 38287061, 2024). "Through the use of a mouse model under chronic viral infection, they defined four subsets of exhausted CD8+ T cells (Tex) according to differential expression levels of CD69 and Ly108 (Slamf6)." (PMID 34943884, 2021).
B cell lymphoma (3 papers, 2016 to 2025). "To study the effect of anti-SLAMF6 on tumor progression we use the aggressive transplantable murine CLL clone TCL1-192 and the B cell lymphoma LMP2A/λMyc into SCID or Rag1−/− mice, respectively." (PMID 27029059, 2016). "Similarly, the progression of a murine B cell lymphoma, LMP2A/λMyc, was also eliminated by an anti-SLAMF6/CD352 monoclonal antibody." (PMID 38612827, 2024).
chronic lymphocytic leukemia (2 papers, 2016 to 2025). "Here we report that upon transplantation of a well-defined aggressive murine B220+CD5+ Chronic Lymphocytic Leukemia (CLL) cell clone, TCL1-192, into SCID mice one injection of a monoclonal antibody directed against SLAMF6 (αSlamf6) abrogates tumor progression in the spleen, bone marrow and blood." (PMID 27029059, 2016).
liver cancer (2 papers, 2021 to 2023). An epithelial or non-epithelial malignant neoplasm that arises from the liver. "Study has shown that SLAMF6 promotes the development of liver cancer by promoting macrophage M2 polarization." (PMID 37907783, 2023). "Previous studies have shown that the expressions of SLAMF1 in cervical cancer and SLAMF6 in liver cancer were closely related to tumor infiltration of immune cells and patient prognosis." (PMID 34733790, 2021).
osteoarthritis (2 papers, 2022 to 2023). A noninflammatory degenerative joint disease occurring chiefly in older persons, characterized by degeneration of the articular cartilage, hypertrophy of bone at the margins and changes in the synovial membrane. "SLAMF6 was increased in osteoarthritis and early RA ST, and in circulating early RA PD-1+CD4+ cells and inhibition of SLAMF6 on CD4+PD-1+ peripheral cells from established RA patients decreased IgG production and plasmablast differentiation." (PMID 38077329, 2023).
pancreas carcinoma (2 papers, 2023 to 2025).
X-linked lymphoproliferative disease (2 papers, 2014 to 2024). X-linked lymphoproliferative disease is a hereditary immunodeficiency characterized, in the majority of cases, by an inadequate immune response to infection with the Epstein-Barr virus (EBV). "However, only development of iNKT cells, but not other hematopoietic cells, is absent in patients with X-linked lymphoproliferative disease (SAP defect) and SAP-deficient mice or reduced in NOD, SLAMF1/SLAMF6 double mutant chimeras and in Fyn deficient mice." (PMID 25142143, 2014).
Burkitt lymphoma (1 paper, 2024). A rare form of malignant mature B-cell non-Hodgkin lymphoma. "The expression of SLAMF6/CD352 by Burkitt lymphoma cell lines was also confirmed by flow cytometry with SLAMF6/CD352 being positive on 80-100% of Daudi, Namalwa, Raji, and Ramos Burkitt lymphoma cells." (PMID 38612827, 2024).
colitis (1 paper, 2016). Inflammation of the colon. "Colitis induced by oral infection with C. rodentium is remarkably reduced in mice lacking both the Rag1 and the SLAMF6 genes compared to their Rag-1-deficient controls, but not in mice that only lack the SLAMF6 gene (single knock out) as compared to their WT littermates." (PMID 26834746, 2016).
hepatocellular carcinoma (1 paper, 2023). A malignant tumor that arises from hepatocytes. "SLAMF6/Ly108 facilitates macrophage M2 polarization, which aids in developing hepatocellular cancer." (PMID 37251372, 2023).
Lewis lung carcinoma (1 paper, 2021). "Indeed, evidence from a recent study utilizing a murine Lewis lung carcinoma model demonstrated that neoantigen-reactive cells within TIL exhibited a TPEX-like PD-1+(DIM) SLAMF6+ phenotype, mirroring that described in human tumours." (PMID 34439399, 2021).
Myelodysplasia (1 paper, 2025). Clonal hematopoietic stem cell disorders characterized by dysplasia (ineffective production) in one or more hematopoietic cell lineages, leading to anemia and cytopenia.
myeloid leukemia (1 paper, 2025). A clonal proliferation of myeloid cells and their precursors in the bone marrow, peripheral blood, and spleen. "Additionally, six of nine tested myeloid leukemia cell lines were found to be positive for SLAMF6." (PMID 41044242, 2025).
osteosarcoma (1 paper, 2019). A usually aggressive malignant bone-forming mesenchymal neoplasm, predominantly affecting adolescents and young adults. "In order to better quantify the contribution of SLAMF6 to cellular adhesion we created a line of U20s osteosarcoma human epithelial cells that stably over expressed SLAMF6 and VCAM-1." (PMID 31199820, 2019).
ovarian carcinoma (1 paper, 2022). A malignant neoplasm originating from the surface ovarian epithelium. "In addition, circ_0000144 and SLAMF6 expression was also notably elevated in the serum of patients with ovarian cancer compared to that in normal samples." (PMID 36243865, 2022). "In addition, we found circ_0000144 and SLAMF6 upregulation in ovarian cancer cell lines (SKOV3, ES-2, and OVCAR3) compared to that in normal human ovarian cells (IOSE80)." (PMID 36243865, 2022).
silicosis (1 paper, 2021). Silicosis is a respiratory disease caused by breathing in (inhaling) silica dust. "In addition, we identified 2 immune response related genes, ROR2 and SLAMF6, which may play important roles in the pulmonary inflammation that accompanies silicosis." (PMID 34149803, 2021).
skin cancer (1 paper, 2020). "SLAMF6 is a possible new target for skin cancer immunotherapy that could help more people to live longer following cancer diagnosis." (PMID 32122464, 2020).
tumor (57 papers, 2008 to 2026). "In vitro and in vivo experiments in mice showed that tumor-associated macrophages (TAMs) had higher levels of SLAMF6 (Ly108), and this was associated with the M2 phenotype." (PMID 38476238, 2024). "SLAMF6 appears to be associated with outcomes in various cancer types and is expressed by various immune cells, with variable anti-tumor effects." (PMID 38476238, 2024). "Here we used Pdcd1 expression (which encodes for PD-1) as a surrogate marker of tumor specificity and observed that indeed, Pdcd1+ Havcr2– Slamf6+ cells were enriched in Tcf7+ cells compared to bulk Pdcd1+ or Pdcd1+ Havcr2– cells." (PMID 32174925, 2020). "Overall, these data reveal that strongly impaired PD-1 inhibition of TCR signalling is required to promote robust effector expansion capable of curbing tumour growth, but such thorough blockade of this inhibitory pathway also caused the loss of high-affinity SLAMF6+ TSL cells." (PMID 41299179, 2026). "Electrotransfection with pCAGGS-SIY-OVAII promoted the infiltration of 4-1BB+ CD107a+ (activated) and Slamf6+ CD127+ (self-replicable) CD8+ T cells in the tumor." (PMID 41348109, 2026). "In contrast, the release of soluble molecules, such as SLAMF6, does confer extra stimulation to engineered T cells and, potentially, to tumor-specific endogenous T cells." (PMID 40558528, 2025). "The inherent expression of SLAMF6 on B cells has generated interest in SLAMF6 as a tumor cell marker on malignancies of the B cell lineage, in a mode similar to CD19 and CD20." (PMID 41044242, 2025). "By flow cytometry we validated the higher expression of Slamf6, a key Tpex marker, in sgElovl1 OT-I T cells infiltrating anti-PD-1-treated tumours compared with control groups." (PMID 40065102, 2025). "The on-target off-tumor activity of an antibody targeting SLAMF6 is, therefore, likely to be limited and clinically manageable." (PMID 41044242, 2025). "Both are described to delineate progenitor exhausted CD8+ T cells from terminally-exhausted CTLs, making SLAMF6-mediated ICS of great interest in rescuing tumour-specific CTLs." (PMID 38440738, 2024). "An analysis in ccRCC focused on regulatory T cells (Tregs) in tumor tissue and found that SLAMF6 is one of four hub genes related to prognosis and Tregs and associated with a better outcome." (PMID 38476238, 2024). "CD8+ T-cell exhaustion is a state of dysfunction that promotes tumor progression and is marked by the generation of Slamf6+ progenitor exhausted (Texprog) and Tim-3+ terminally exhausted (Texterm) subpopulations." (PMID 38287103, 2024). "For instance, GSK2879552 increased the abundance of Slamf6+Tim-3− Texprog cells in MC38-OVA tumor-bearing recipients in the adoptive transfer models." (PMID 38287103, 2024). "Our findings showed that expression of cDC1-related genes were significantly increased in the high SLAMF6 group than in the low SLAMF6 group, indicating that SLAMF6 expression in the tumor correlates with cDC1s density in the tumor." (PMID 38287061, 2024). "High expression of SLAMF6 is associated with increased expression of Teff-related genes and TCF7 which marks tumor-infiltrating T cells with stem cell-like properties." (PMID 38287061, 2024). "Here, we investigated the impact of SLAMF6 expression on prognosis in two immunologically different tumor types using publicly available databases." (PMID 38287061, 2024). "These included a major Prf1highGzmhighPdcd1+Havcr2+ cluster resembling “exhausted” T (TEX) cells and a Pdcd1+Tcf7+Slamf6+ cluster resembling “stem-like” T cells, that were predominantly tumour-resident and expanded with anti-PD-L1." (PMID 38267413, 2024). "Taken together, these results demonstrate that the Tcf3-Tal1 complex dominates in the absence of the Id2 HLH domain and recruits LSD1 to alter chromatin accessibility at the Slamf6 promoter during the Texprog-to-Texterm conversion in tumor immune evasion." (PMID 38287103, 2024).
tumor (continued). "We followed expression of Slamf6 and PD-1 on Ptpn22WT and Ptpn22KO cells from PE over the entire time-course of tumor exposure as indicators of stemness and terminal effector/exhaustion, respectively." (PMID 38056892, 2023). "We then examined the surface expression levels of IL-17RA and IL-17RC on two CTL subsets of tumor-infiltrated lymphocytes (TILs) based on the surface markers of Slamf6 and Tim3." (PMID 37605139, 2023). "We observed that in the course of tumor progression that the proportion of both the antigen specific tetramer positive population and the SLAMF6+CD69+ progenitor population were progressively diminished." (PMID 37914685, 2023). "PKM2 knockout (PKM2KO) T cells following co-culture with HKP1-ova-GFP tumor cells showed higher levels SlamF6 and TCF1 with concomitant decreases in GzmB, IFNγ, and TNFa." (PMID 37790365, 2023). "The lymph node batch in turn showed higher expression of stemness markers in the draining lymph nodes and Slamf6 in the tumor side." (PMID 37301772, 2023). "We conclude that SLAMF6 bispecific antibodies have a role in modulating T cell responses, and future work will evaluate the therapeutic potential in tumor models." (PMID 36622343, 2022). "Future work will focus on obtaining humanized mice and/or synthesizing mouse-specific antibodies to better evaluate the therapeutic potential of bispecific SLAMF6 activating antibodies in tumor immunology." (PMID 36622343, 2022). "On day 7, Pmel-1 cells or Pmel-1 x SLAMF6 -/- cells were adoptively transferred i.v. into the irradiated tumor-bearing mice." (PMID 32122464, 2020). "In conclusion, selection of CD39– Tim3– Slamf6+ PD-1+ TILs by surface antibody staining allows for maximum enrichment of Tcf1+ tumor-specific Tpe." (PMID 32174925, 2020). "We confirmed that CD39– Tim3– Slamf6+ PD-1+ cells showed the highest enrichment for Tcf1+ cells in both endogenous and transferred tumor-specific OT1 cells, which accounted for the ~3.5% of total endogenous or OT1 TILs." (PMID 32174925, 2020). "A previous report already showed that tumor-specific (identified by tetramer staining) Tim3- Slamf6+ cells were enriched in Tcf7+ cells compared to Tim3+ Slamf6- counterparts." (PMID 32174925, 2020). "The data obtained identify SLAMF6 as a receptor whose absence significantly improves CD8+-mediated tumor regression, suggesting that it is an inhibitory checkpoint." (PMID 32122464, 2020). "Cross species comparative analysis with aCGH data of human cancer cell lines revealed known and candidate oncogenes (Mmp13, Slamf6, and Rreb1) and tumor suppressors (Wwox and Arfrp2)." (PMID 18485879, 2008). "Thus, this is the first study to demonstrate that breaking the SLAMF6 interaction is sufficient to induce T cell activation and killing of tumor cells." (PMID 41044242, 2025). "Our study is the first to examine the role of endogenous human SLAMF6 on tumor cells." (PMID 41044242, 2025). "However, in HCC progenitor exhausted CD8+ T cells have been demonstrated ex vivo by PD1int, TCF-1+, TOXlo expression, providing a potential reservoir for SLAMF6-mediated ICS to reinvigorate anti-tumour immunity." (PMID 38440738, 2024). "Indeed, it's essential to understand the precise intracellular signaling pathways induced by SLAMF6 engagement in the tumor microenvironment, especially if therapeutic targeting is considered." (PMID 38287061, 2024). "Here, we hypothesize that high expression of SLAMF6 in the tumor correlates with higher immune activities and better clinical outcome." (PMID 38287061, 2024). "Considering that Texprog cells but not terminally exhausted T cells can respond to anti-PD-1 therapy, we treated tumor-bearing mice with PD-1 blockade and found that Id2 deletion impaired the generation or maintenance of Slamf6+ Texprog cells that can respond to PD-1 blockade." (PMID 38287103, 2024).
tumor (continued). "Tumor-infiltrating OT1s across treatment groups could be divided into Slamf6+CD39– Texprog and Slamf6–CD39+ cells encompassing Texint, Texeff, and terminally differentiated Texterm CD8+ subsets." (PMID 38099496, 2023). "By contrast, CD4+ Th cells from CAR T-vax-treated mice upregulated genes associated with Th1 function (Ifng, Cxcr3) and self-renewal (Slamf6, Tcf7), suggesting that the vaccine may also promote anti-tumor phenotypes among CD4+ TILs." (PMID 37413990, 2023). "In the tumor bed, stem-like exhausted CTLs, which were defined as PD-1+Slamf6+Tim3−, expressed higher IL-17A receptor heterodimers and lower leukocyte function-associated antigen-1 (LFA-1) than terminally exhausted CTLs did, that were defined as PD-1+Slamf6−Tim3+." (PMID 37605139, 2023). "Similarly, within E0771 tumor cells it was observed that A2AR expression was significantly higher on SLAMF6+CD39− or SLAMF6−CD39+ cells relative to SLAMF6−CD39− counterparts." (PMID 37914685, 2023). "Expression of SLAMF6 was significantly higher in tumor tissues." (PMID 36243865, 2022). "Indeed, we observed by flow cytometry that CD39– Tim3– Slamf6+ PD-1+ cells yielded maximum enrichment for tumor specific PD-1+ Tcf1+ OT1 TILs in B16.OVA tumors." (PMID 32174925, 2020). "Altogether, we show that selection of CD39– Tim3– Slamf6+ PD-1+ TILs enables enrichment of tumor specific Tcf1+ PD-1+ TILs Tpe that may enhance efficacy of adoptive cell transfer therapies in cancer patients." (PMID 32174925, 2020). "Antibodies targeting SLAMF6 have demonstrated efficacy in mouse oncology models, underscoring the therapeutic potential of targeting this receptor and highlighting the potential of NK cells to play a critical role in anti-tumor immunity." (PMID 31360302, 2019). "The data indicate that removal of the tumor cells by a mouse anti-mouse Slamf6 (αSlamf6) antibody (13G3), see Materials and Methods) relies on antibody dependent cell-mediated cytotoxicity (ADCC) and co-stimulation of B cell receptor (BCR) signaling, which is of importance to progression of CLL." (PMID 27029059, 2016). "By contrast, Teff cell expansion was only marginally affected in both the tdLN and the spleen, with negligible effect in the tumour, showing that late antigen presentation by cDC1 cells in the tdLN is necessary for maintaining an expanded population of antigen-specific SLAMF6+ TSL cells." (PMID 41299179, 2026). "In addition to Slamf7 staining, Slamf6 and Nkg2d immunostaining were more spread out in ST-5-002-treated mice compared with those in mice that did not receive isoxazole treatment, which were more restricted to non-tumor regions." (PMID 39828766, 2025). "The recent demonstration that alternative splicing of SLAMF6 in humans could be steered by the use of antisense oligonucleotides, thereby increasing anti-tumor effect of tumor infiltrating lymphocytes, is further evidence of the importance of this field of study." (PMID 36902453, 2023). "Key immune activation and tumor suppression genes including CD2, CD3, CD247 (CD3 zeta chain), CD48, CD84, CCL19, CXCL10, and SLAMF6 were consistently upregulated in the hot phenotype across all ancestries." (PMID 41387728, 2025). "CD352, also known as SLAMF6, is a homotypic binding receptor expressed on both resting and activated PBMC, and its absence significantly ameliorated CD8+T cells mediated tumor regression, suggesting that it serves as an inhibitory checkpoint." (PMID 40040705, 2025). "Further, knockout of cGAS-STING in CD8+ T cells accelerated tumor progression, reduced T cell proliferation and cytokine production, and diminished expression of stemness markers, TCF1 and SLAMF6 (Ly108)." (PMID 40948803, 2025). "We found that 9D9 increased the absolute numbers of tumor-infiltrating CD44+PD-1+ CD8+ T cells, stem-like/progenitor exhausted (SLAMF6+TIM3−) and effector/terminally exhausted (SLAMF6−TIM3+) CD8+ T cells." (PMID 40460830, 2025).